U4 (U4 spliceosomal RNA )
Synonyms: LOC124904686
Gene: Small nuclear RNA gene on chromosome 1 (155,894,281 to 155,894,386, forward strand). Ensembl gene ENSG00000283442.
Gene Ontology:
Molecular function: U6 snRNA binding
Biological process: formation of quadruple SL/U4/U5/U6 snRNP; spliceosomal tri-snRNP complex assembly
Cellular component: U4 snRNP; U4/U6 x U5 tri-snRNP complex
Homologues: Orthologues: chimpanzee U4 (100% identical), pig U4 (73% identical), tropical clawed frog U4 (71% identical). Paralogues in human: RNU4-10P (86% identical), RNU4-49P (81% identical), RNU4-81P (78% identical), RNU4-17P (77% identical), RNU4-32P (77% identical), RNU4-11P (76% identical), RNU4-15P (76% identical), RNU4-50P (76% identical), RNU4-51P (76% identical), RNU4-46P (75% identical), RNU4-24P (70% identical), RNU4-52P (70% identical), and 82 more.
Diseases named in the same sentence as U4 in open-access papers:
U4 is named in the same sentence as 4 diseases in open-access papers, as found by Europe PMC text mining. Sharing a sentence is not in itself a finding about the gene and the disease. The quoted sentences say what the papers report.
breast carcinoma (1 paper, 2022). "LASTR, upregulated in hypoxic breast cancer, contributes to triple-negative breast cancer cell fitness by regulating the activity of the U4/U6 recycling factor SART3." (PMID 35495133, 2022).
cancer (1 paper, 2021). A tumor composed of atypical neoplastic, often pleomorphic cells that invade other tissues. "Remarkably, DDX23 has been discovered as a component of the U4/U6-U5 tri-snRNP complex involved in pre-mRNA splicing in cancer progression." (PMID 33990545, 2021).
U4 also shares sentences with these, for which no sentence is quoted: triple-negative breast carcinoma (1 paper); tumor (1).